SND1 (staphylococcal nuclease and tudor domain containing 1)
Diseases named in the same sentence as SND1 in open-access papers (continued):
Sharing a sentence is not in itself a finding about the gene and the disease.
tumor (continued). "Knocking down SND1 in AEG1+/+ cells reduced the sphere formation in vitro and tumor formation in vivo, resembling the phenotype of AEG1−/− cells." (PMID 25405367, 2015). "Silencing SND1 in CRC cells significantly decreased in vitro cell invasion and in vivo tumor metastasis, which was similar to the phenotype induced by miR-361-5p." (PMID 25965817, 2015). "As AEG-1 has been demonstrated to interact with SND1 and enhance the activity of RISC, it increases degradation of tumor suppressor mRNAs that are target of onco-miRs." (PMID 22060137, 2011). "In addition to chaperones, which were shown to play a significant role for the induction of anti-tumor immune responses, we identified a number of TAAs interacting with NS1 (i.e., TPT1, NUMA1, SPRYD4, SND1, and GNL3)." (PMID 36680249, 2023). "However, when PGAM5 was knocked down, SND1-enhanced cell proliferation, tumor growth and weight of Hep3B xenografts were markedly reduced, suggesting that PGAM5 was critical for SND1-regulated cell growth in vitro and tumor growth in vivo." (PMID 35433434, 2022). "More importantly, the binding ability of SND1 and PGAM5 was further enhanced upon FCCP or glucose deprivation treatment, suggesting that the binding of SND1 and PGAM5 plays an important role within the tumor microenvironment." (PMID 35433434, 2022). "Indeed, binding of MTDH and SND1 stimulates the RISC activity and consequently facilitates the gene silencing of tumor suppressor mRNAs via either small interfering RNA (siRNA) or microRNA (miRNA) processes." (PMID 33802672, 2021). "A selective SND1 inhibitor, 3′,5′-deoxythymidine bisphosphate (pdTp), inhibited the AEG-1-induced increased proliferation of human HCC cells and effectively reduced the tumor burden in human xenograft models of subcutaneous or orthotopic HCC." (PMID 33918653, 2021). "In vivo studies with hepatocyte specific SND1 over-expressing mice (Alb/SND1) showed that transgenic animals have a higher incidence of spontaneous tumors, an increase in CD133+, CD44+ and EpCAM+ tumor initiating cells (TICs) and an increase in HCC drivers (c-Myc, TNFα and IL-6)." (PMID 32258418, 2018). "This included hypermethylation of negative TMRs associated with tumour suppressor genes, such as TGFBR2 and SMAD3, as well as loss of methylation at negative TMRs for the oncogenes ERBB3 and SND1 and for PTPN13, which is described as having both oncogenic and tumour suppressor roles." (PMID 41036619, 2025). "Mechanistically, we showed that AEG-1 palmitoylation adversely regulates its protein stability and weakens AEG-1 and staphylococcal nuclease and tudor domain containing 1 (SND1) interaction, which might contribute to the alterations of the RISC activity and the expression of tumor suppressors." (PMID 36276642, 2022). "AEG-1 mutants, which failed to interact with SND1, lost their tumor-initiating potential." (PMID 33918653, 2021).
infection (9 papers, 2017 to 2026). The state of being infected such as from the introduction of a foreign agent such as serum, vaccine, antigenic substance or organism. "Taken together, the data suggest that SND1 deficiency in mice resulted in significantly impaired conventional DC number and phenotype, which are closely related to DC function against Cm infection." (PMID 33635920, 2021). "Our data showed that SND1-/- mice exhibited significantly greater body weight loss, higher organism growth, and more severe pathological changes compared with wild-type mice following the infection." (PMID 33635920, 2021). "The results showed that following Cm infection SND1-/-mice suffered more severe disease compared with heterozygous SND1+/- and control C57BL/6 control mice." (PMID 33635920, 2021). "Consistently, SND1-/- mice showed significantly higher bacterial loads in the lung than SND1+/- and wild-type mice at day 7 of infection." (PMID 33635920, 2021). "To further investigate the influence of SND1 on subsets of DCs, we examined the changes in the frequencies of DC subsets in spleen and lung after Cm infection." (PMID 33635920, 2021). "First, the lungs from wild-type and SND1-/- mice were comparable before or after Cm infection in the total cell number." (PMID 33635920, 2021). "The percentage and absolute cell number of the splenic IL-12+ CD8+ CD11b- CD11c+ DC subset and IL-12+ CD8- CD11b+ CD11c+ DC subset were decrease significantly in SND1-/- mice after Cm infection." (PMID 33635920, 2021). "We discover that NSP9, a viral RBP and direct SND1 interaction partner, is covalently linked to the 5′ ends of positive- and negative-sense RNAs produced during infection." (PMID 37794589, 2023). "Notably, the exponential phase of viral RNA synthesis occurs 3–6 h after infection, matching the time window in which we observe RNA synthesis defects in SND1-depleted cells." (PMID 37794589, 2023). "Finally, the slightly lower inflammatory tone of DCs in SND1-/- mice was also observed under naïve condition, albeit to a lesser degree than infection, it is necessary to analyze how and why SND1 regulates DC function via a certain molecular mechanism." (PMID 33635920, 2021). "The most intriguing finding in the current study is the crucial modulating effect of SND1 on the cytokine production, phenotype, and, more importantly, function of DC in a real infection mouse model, and the significant effect of this modulation on T cell responses and protection in vivo." (PMID 33635920, 2021). "Based on our data, we think it is possible that, in the beginning of infection, SND1 may influence DC function through a direct effect." (PMID 33635920, 2021). "Notably, the currentt study has focused on the role of SND1 in early phases of infection." (PMID 33635920, 2021). "Induction extends from 1 to 2 days post infection in the case of PDIP_00580 (transcription factor C6), PDIP_01590 (LYR protein), PDIP_49640 (Snd1/p100), and PDIP_64910 (rhodanese protein)." (PMID 38667906, 2024). "We observed delayed viral growth early during the infection cycle (0–16 hpi), as well as a reduced production of SARS-CoV-2-GFP virus in SND1 KO cells." (PMID 37794589, 2023). "To resolve how SND1 depletion affects viral RNA production, we measured changes in SARS-CoV-2 gRNA and sgmRNA levels in 2-h intervals, early during the infection cycle." (PMID 37794589, 2023). "Splenic SND1-/- DCs showed lower expression of CD40, CD80 and CD86 molecules than splenic wild-type DCs especially at day 7 following infection both in frequency and mean fluorescence intensity." (PMID 33635920, 2021). "First, DC isolated from SND1-/- mice exhibited significantly lower CD40/CD80/CD86 expression and IL-12 production, but higher IL-10 production than wild-type mice during Cm infection." (PMID 33635920, 2021).
infection (continued). "Upon infection of SND1 KO cells with SARS-CoV-2, we noted reduced double-stranded RNA (dsRNA) accumulation and diminished viral RNA replication compared to control cells that was most pronounced at early infection time points." (PMID 37794589, 2023). "To analyze the potential role of Snd1 in this ERG-mediated phenotype, we isolated ERG-overexpressing and control primary prostate epithelial cells from mice with conditional Snd1 and deleted Snd1 using Adenovirus-Cre infection ex vivo." (PMID 37973913, 2023). "More importantly, we found that the SND1-/- mice have impaired function of splenic CD8+ DC and pulmonary CD103+ DC, enhanced expansion of Treg cells, and reduction of Th1/17 protective immunity against the Cm infection." (PMID 33635920, 2021). "More importantly, we showed that DC isolated from SND1-/- mice, unlike those from wild-type mice, failed to generate protective Th1/17 responses and failed to protect the recipient mice against challenge infection." (PMID 33635920, 2021). "Although it is obvious that this study shows a critical role of SND1 in protection, it does not necessarily mean that SND1 at late phases of infection are also beneficial from other genetic background." (PMID 33635920, 2021). "At later infection time points, gRNA and sgmRNA are not differentially affected by SND1 KO." (PMID 37794589, 2023).
bacterial infection (2 papers, 2021 to 2022). "Our data provide new insight into the mechanism by which SND1 plays a role in host defense against intracellular bacterial infection." (PMID 33635920, 2021). "To date, no reports have been linked SND1 to immune response against bacterial infection." (PMID 33635920, 2021).
renal disease (1 paper, 2023). "We also identified 3 proteins, (Staphylococcal nuclease domain-containing protein 1 (SND1), glycogen debranching enzyme (AGL) and marginal zone B- and B1-cell-specific protein (MZB1) that were associated with the presence of active renal disease." (PMID 37516862, 2023).
SND1 also shares sentences with these, for which no sentence is quoted: adenoma (1 paper); colon adenocarcinoma (1); diabetes (1); diffuse large B-cell lymphoma (1); knee osteoarthritis (1); liver (1); lymph node metastasis (1); lymphoid neoplasm (1); myocardial infarction (1); nasopharyngeal carcinoma (1); oncocytoma (1); pancreatic acinar carcinoma (1); pancreatic adenocarcinoma (1); pancreatic ductal adenocarcinoma (1); pituicytoma (1); prostatic intraepithelial neoplasia (1); psoriasis (1); psychiatric disorder (1); sarcoma (1); skin cutaneous melanoma (1); steatosis (1); testicular germ cell tumor (1); thymoma (1); thyroid cancer (1).